INS (insulin)
Diseases named in the same sentence as INS in open-access papers (continued):
Sharing a sentence is not in itself a finding about the gene and the disease.
Insulin resistance (continued). "The expression of certain miRNAs targeting the insulin signaling molecules is modulated aberrantly in diet-induced obesity, which participates actively in the pathogenesis of insulin resistance." (PMID 27900351, 2016). "In a similar study, the pivotal role for the IGF-1 in insulin sensitivity has received further support from liver-specific IGF-1 KO mice which exhibited overt insulin resistance and hyperinsulinaemia that was reversed by the administration of IGF-1." (PMID 26733412, 2016). "The continuous changes in insulin resistance indices during high-risk stages (Q3 and Q4) are consistent with the trajectory showing that HOMA insulin sensitivity decreased steeply until the diagnosis of T2D." (PMID 27298712, 2016). "The treatment of insulin resistance and hyperinsulinemia includes the use of insulin-sensitizers (metformin, thiazolidinediones, and inositols)." (PMID 27725832, 2016). "Dietary patterns which induce excessive insulin secretion are believed to contribute to worsening insulin resistance and beta-cell dysfunction." (PMID 27070641, 2016). "Insulin resistance promotes a compensatory increase in insulin levels via pancreatic β cell proliferation and enhanced insulin secretion to maintain homeostasis." (PMID 27226575, 2016). "Several pathways contribute to the etiology of insulin resistance at a cellular level, including defective insulin signal transduction, impaired effector molecules within insulin-dependent pathways, and enhanced insulin-antagonizing pathways." (PMID 26993044, 2016). "Type II diabetes mellitus is characterized by insufficient insulin secretion and insulin resistance." (PMID 27034961, 2016). "Defects in insulin‐mediated glucose uptake in skeletal muscle contribute to whole‐body insulin resistance in obesity and precedes the development of type 2 diabetes." (PMID 26733245, 2016). "Insulin resistance, which is an impaired response of insulin-sensitive tissues to insulin signalling, is a characteristic feature of T2DM and plays a key role in the pathogenesis of the disease." (PMID 27929385, 2016). "Normally, the liver plays a key role in glucose metabolism, and impaired insulin signaling is pivotal for the development of insulin resistance." (PMID 27189109, 2016). "High IL-10 levels, for example, have been reported to promote insulin sensitivity in humans and protect against insulin resistance by diminishing TNF mediated intracellular signaling in adipocytes." (PMID 27239103, 2016). "Recently, we have demonstrated that upregulation of DDAH expression by the bile acid derivative farnesoid X receptor (FXR) agonist INT-747 improves insulin sensitivity in an animal model of salt-sensitive hypertension and insulin resistance." (PMID 26770984, 2016). "Significant positive correlations between BMIwith fasting insulin (r=0.493) and insulin resistance(r=0.401, P˂0.01) and a significant negativecorrelation with LH (r=-0.279, P˂0.01)were found in PCOS patients." (PMID 27123196, 2016). "Reduced insulin sensitivity leads to insulin resistance, which in turn can lead to the development of type 2 diabetes." (PMID 28123923, 2016). "One of the limitations of our study is the measurement of plasma insulin and C-peptide levels as markers of insulin resistance, which are only surrogate markers of insulin resistance." (PMID 26910627, 2016). "Growing evidence suggests that activation of JNK, NF-κB, and proinflammatory cytokines is central to interposing insulin resistance through inhibition of insulin receptor signaling and suppression of organ insulin sensitivity." (PMID 27563875, 2016). "Insulin resistance (IR) is a physiological condition in which insulin hormone finds less ability in reducing blood sugar." (PMID 27994997, 2016). "IL-6 also plays a direct role in insulin resistance by inhibiting insulin receptor signal transduction and insulin action in hepatocytes." (PMID 27213439, 2016).
Insulin resistance (continued). "Adiponectin is an adipocyte-derived hormone whose circulating levels are closely and inversely related to insulin concentration and insulin resistance, and is a good reflection of whole body insulin sensitivity." (PMID 26768001, 2016). "The results imply that in obesity-related hypoxia DPP4 is abundantly expressed, contributing to the reduction in insulin activity and thereby to the onset of insulin resistance in these subjects." (PMID 26881257, 2016). "In simple terms, insulin resistance is a condition in which cells fail to appropriately respond to circulating insulin." (PMID 28101517, 2016). "The non-obese T2DM phenotype is characterized by a more pronounced reduction in insulin secretion and less severe insulin resistance as compared to obese T2DM patients." (PMID 27496100, 2016). "Obesity is associated with an increased release of free fatty acids (FFAs) and an abnormal secretion of adipokines, which can adversely affect how insulin acts; therefore, both FFAs and adipokines potentially link obesity with insulin resistance." (PMID 26752053, 2016). "Although insulin resistance and increased oxidative stress are believed to be major risk factors for the progression to NASH many agents, including insulin sensitizers, have been evaluated with disappointing results in the management of NASH." (PMID 27347998, 2016). "Replacing carbohydrate with MUFA lowered HbA1c (-0.09%; -0.12, -0.05; n = 23), 2 h post-challenge insulin (-20.3 pmol/L; -32.2, -8.4; n = 11), and homeostasis model assessment for insulin resistance (HOMA-IR) (-2.4%; -4.6, -0.3; n = 30)." (PMID 27434027, 2016). "At higher values of insulin resistance individuals remain glucose tolerant only if their pancreas is able to react with a compensatory hypersecretion of insulin." (PMID 27344314, 2016). "Girls had significantly higher levels of adiposity (fat mass index), insulin, homeostatic model assessment of insulin resistance values, triglyceride and C‐reactive protein." (PMID 26498636, 2016). "When ovariectomized mice are treated with estradiol, to mimic estrogen replacement therapy in postmenopausal women, it improves both hepatic and muscle insulin sensitivity suggesting that estrogen is functioning to prevent insulin resistance." (PMID 27695036, 2016). "The apparent paradox between pathological insulin resistance and the benefits of acute disruption of insulin signaling is a complex topic requiring further research attention." (PMID 27303627, 2016). "We performed analyses of fat mass, fat free mass, plasma (p)-glucose, p-insulin, Homa-Index (a measure of insulin resistance), serum (s)-leptin, s-ghrelin and of the hypothalamic volume in scans obtained by magnetic resonance imaging (MRI) at 3 Tesla." (PMID 26824435, 2016). "The genesis of DM can occur due to defects in insulin secretion by the pancreas, defects in insulin’s target cells (insulin resistance), or a combination of both events." (PMID 26910629, 2016). "Glucose and insulin tolerance tests indicated that 6-month-old SL mice presented impaired glucose tolerance and insulin resistance." (PMID 27465434, 2016). "Obesity related GDM is initially associated with insulin resistance whereas in lean women an inadequate insulin secretory response to the physiological state of insulin resistance in pregnancy is considered predominant." (PMID 27930697, 2016). "In agreement with this notion, acute rapamycin injection not only markedly improved insulin sensitivity in AdicerKO mice on the AL diet, but also completely reversed insulin resistance of these mice under the DR regimen." (PMID 27241713, 2016). "The feature of Type 2 DM is the partial or complete failure in using insulin (insulin resistance) even though the functional insulin is available and then causes hyperglycemia." (PMID 27588252, 2016). "Tolerance tests give more accurate information than homeostasis model assessment of insulin resistance to determine insulin sensitivity." (PMID 26937247, 2016).
Insulin resistance (continued). "It is believed that increased insulin resistance during the aging process results in a compensatory increase in insulin secretion, but eventually defective and decreased insulin secretion can occur." (PMID 27441644, 2016). "On the condition of obesity and its related metabolic abnormalities, the impaired insulin signaling pathway usually leads to insulin resistance." (PMID 27242533, 2016). "Maternal and perinatal Mg restriction in rats induced insulin resistance and decreased insulin response to a glucose challenge." (PMID 27136580, 2016). "Second, insulin therapy is significantly limited by the phenomenon of insulin resistance that is induced by both acute and chronic disease processes." (PMID 30202553, 2016). "In these exploratory analyses, the data demonstrated that supplementation with CDNC markedly reduced insulin (27.1%) and insulin resistance (35.4%) compared to the baseline levels." (PMID 27687012, 2016). "Insulin resistance plays a central role in the pathogenesis of these disorders, through defects in insulin-mediated glucose uptake and/or glucose release by the liver, muscles, and other peripheral tissues." (PMID 26788116, 2016). "Compared with OB group, AN group had higher levels of fasting insulin and homeostasis model of assessment for insulin resistance (HOMA-IR) (P < 0.05), but lower serum levels of blood glucose." (PMID 27190511, 2016). "Another well-known side effect of insulin-based regimen is weight gain, which secondarily increases insulin resistance." (PMID 27391319, 2016). "Once insulin resistance begins, the insulin sensitivity of target cells decreases, and the insulin signal transduction pathway becomes disordered." (PMID 27187341, 2016). "In experimental animals, activation of SIRT1 was reported to offer protection against obesity and insulin resistance by positively regulating the secretion of insulin." (PMID 28050570, 2016). "T2DM is a chronic disease characterized by disruption of insulin secretion by pancreatic beta cells, insulin resistance in peripheral tissues, or both together." (PMID 27882332, 2016). "The plasma glucose, cholesterol, triglyceride levels, insulin resistance and glucose tolerance were reduced, and the degree of insulin secretion in rat plasma was significantly increased upon GBRE treatment." (PMID 28036014, 2016). "Differently from T1D, type 2 diabetes (T2D) is a metabolic disorder related to obesity and characterized by insulin resistance i.e., decreased action of insulin in muscle, liver and adipose tissue, and failure of β-cells to maintain sufficient insulin levels." (PMID 27356471, 2016). "Administration of exogenous MG (50–75 mg/kg, daily, i.p.)induced insulin resistance in mice, inhibited insulin-stimulated phosphorylation of protein kinase B and extracellularly-regulated kinase, contributing to insulin resistance in muscle cells." (PMID 27338619, 2016). "On the other hand, GH treatments have been reported to increase insulin resistance with the over-secretion of insulin occurring to compensate." (PMID 27799945, 2016). "Both the SH and GSH animal groups also exhibited a markedly lower HOMA-IR index—an indicator of insulin resistance—than the control group, suggesting an increase in the insulin sensitivity in these animals." (PMID 27775654, 2016). "Reduction of plasma insulin level, improvement of insulin tolerance, and increase of glucose infusion rate supported systemic improvement of insulin resistance by BCH treatment in HF/HFr-fed mice." (PMID 27874078, 2016). "The NIOR has already been used to identify a correlation between the variants of genes (associated with the metabolism of carbohydrates and fat) and the output of insulin and the development of diet-induced insulin resistance." (PMID 27455252, 2016). "Patients taking MYO-INS experienced a significant improvement of reproductive axis (p < 0.05) and insulin resistance (p < 0.05) state after 12 weeks of supplementation." (PMID 27688754, 2016).
Insulin resistance (continued). "Both groups decreased plasma insulin (SG: −35.3 %, P = 0.01, CG: −22.6 %, P = 0.02) and homeostasis model of assessment - insulin resistance (HOMA-IR) (SG: −39.2 %, P = 0.007, CG: −21.8 %, P = 0.04) at 6-months from baseline." (PMID 27090218, 2016). "Obesity induces hormonal abnormalities and peripheral insulin resistance (IR), which can alter central insulin signaling and lead to AD-like cognitive impairment." (PMID 27936074, 2016). "Insulin resistance in bone, due to decreased osteocalcin activity, leads to decreased tissue sensitivity to insulin." (PMID 26950142, 2016). "ISI and GSI have been shown to correlate well with the insulin sensitivity index obtained from the euglycemic hyperinsulinemic clamp, the gold standard for measurement of insulin resistance." (PMID 27736893, 2016). "Spermatozoa insulin resistance state is manifested by increased spermatozoa insulin gene expression, as well as increased seminal plasma insulin and glucose levels." (PMID 27891185, 2016). "The homeostatic model assessment (HOMA-IR) is a validated method to measure insulin resistance from fasting glucose and insulin." (PMID 27872738, 2016). "The different trajectories rank HOMA insulin sensitivity (or insulin resistance, assessed by HOMA-IR) higher than FG and A1c as a potential marker for identifying earlier stage of prediabetes." (PMID 27298712, 2016). "Results showed that subordinate mice displayed a drastic downregulation of the insulin pathway in liver and muscle, indicative of insulin resistance, already on standard diet." (PMID 26946982, 2016). "There is profound cardiac insulin resistance in HF, with decreased insulin‐dependent glucose uptake, but normal or increased insulin‐independent glucose uptake." (PMID 26993743, 2016). "Previous studies have shown that inactivation of Akt can lead to insulin resistance, decreased β cell mass, and impaired insulin secretion." (PMID 27034691, 2016). "Fructose supplemented rats, both after 6 and 12 weeks of the special diet, showed higher insulin levels when compared to control groups, indicating that 6 weeks of fructose supplementation is sufficient to induce insulin resistance in Wistar rats." (PMID 26799836, 2016). "Type 2 diabetes is induced when enhanced insulin secretion cannot compensate for increasing levels of insulin resistance." (PMID 26884795, 2016). "This is a concept similar to those of insulin resistance, in which there is a compensatory rise in serum insulin levels to increase GLUT 4 translocation to the cell membrane in skeletal muscle and adipose tissue." (PMID 27550417, 2016). "The expression of PDK4 is sensitive to insulin, as insulin resistance results in an upregulation of PDK4 expression." (PMID 27649241, 2016). "Insulin resistance (IR) is characterized by suboptimal biological responses of the liver, skeletal muscle and adipose tissue to normal amounts of insulin secreted." (PMID 27770799, 2016). "This inhibitory effect contributes to increased Aβ levels, thought to be a key contributor to AD42, 43, as well as to increased insulin levels, a known correlate of insulin resistance in T2DM/MetS." (PMID 26743041, 2016). "Insulin resistance was calculated by finding the percent decrease in glycaemia after injecting animals with insulin." (PMID 27401171, 2016). "Increased hepatic insulin resistance also increases insulin release from pancreas as a compensatory mechanism." (PMID 27818793, 2016). "Corticosteroids induce both acute and chronic insulin resistance, and this is measured by fasting glucose and insulin levels." (PMID 27530235, 2016). "Both steatosis and insulin resistance activate connective tissue growth factor (CTGF), but steatosis does so by increasing inflammation while insulin resistance does so by increasing glucose and insulin levels." (PMID 27231906, 2016).
Insulin resistance (continued). "In agreement with the cohort study, animal studies also show a higher risk for male offspring, but not as much for female offspring, as seen by increased body weight, increased insulin levels and insulin resistance from BPA exposure." (PMID 29051427, 2016). "In T2D, there is insufficient insulin to meet the increased demand resulting from insulin resistance that is usually induced by obesity." (PMID 27935966, 2016). "Inflammation sustains insulin resistance, results in compensatory increase of insulin levels in T2D, and contributes to the destruction of pancreatic β cells in T1D." (PMID 27240327, 2016). "In type 2 diabetes, insulin resistance places a greater demand on pancreatic β-cells to secrete more insulin." (PMID 26878317, 2016). "This study was planned to determine the early alterations in indices of glucose homeostasis (glucose, insulin, and cortisol) in term and preterm newborns and the correlations of glucose, insulin, and cortisol levels with insulin resistance indices." (PMID 27087404, 2016). "Participants met the criteria for hyperinsulinemia (fasting insulin > 180 pmol/L) and insulin resistance (HOMA-IR value > 2.5)." (PMID 27472361, 2016). "Several pathological features, including insulin resistance, disrupted insulin signaling, and inflammation, appear to be shared by patients with T2DM and AD." (PMID 27895978, 2016). "Sustained insulin signalling in the fasting state appears to be an essential component in the development of ‘selective insulin resistance'." (PMID 27708333, 2016). "First, pubertal insulin resistance, characterized by a decrease in peripheral insulin sensitivity accompanied by a lower increase in acute insulin response, emerges as early as at age 7 years." (PMID 27834901, 2016). "Type 2 diabetes is a heterogeneous disorder that develops as a result of relatively inappropriate insulin secretion and insulin resistance." (PMID 27656657, 2016). "Another study used lard as a source of fat; feeding adult flies a lard-based HFD induced the accumulation of fat, a progressive increase in glucose levels (hyperglycemia), impaired insulin sensitivity (insulin resistance) and a decreased lifespan." (PMID 27604692, 2016). "BMI, waist circumference, blood pressure, fat and lean mass (by dual-energy X-ray absorptiometry), TAG, HDL-cholesterol, glucose, insulin, homeostatic model assessment–insulin resistance index (HOMA-IR), food intake and physical activity were measured." (PMID 25990645, 2016). "Elevated circulating glucose levels (hyperglycemia) and T2D result from a mismatch of insulin demand and activity, for example β-cell dysfunction in the face of insulin resistance." (PMID 27053133, 2016). "In good agreement with previous studies, SOY group manifested a lower insulin level and insulin resistance (HOMA-IR) than the other two groups." (PMID 27763537, 2016). "The impairment in insulin secretion by β-cell dysfunction and insulin action by increased insulin resistance contributes to T2DM-induced hyperglycemia." (PMID 26978332, 2016). "In this cross-sectional study, we estimated the levels of cord blood glucose, insulin, and cortisol in term and preterm newborns and the correlations between glucose homeostasis indices and insulin resistance markers." (PMID 27087404, 2016). "Early on in T2D development, insulin resistance leads to compensatory elevation of insulin secretion, which counteracts the decrease in tissue sensitivity and maintains normal blood glucose levels by stimulating uptake by tissues such as adipose and liver." (PMID 27053133, 2016). "The major pathogenesis of T2DM is insulin resistance, which is the resistance of target tissues to insulin action, and has been suggested to play a key role in the cluster of diabetic complications including atherosclerosis, and diabetic nephropathy (DN)." (PMID 26739836, 2016).